MGMT (O-6-methylguanine-DNA methyltransferase)
Diseases named in the same sentence as MGMT in open-access papers (continued):
Sharing a sentence is not in itself a finding about the gene and the disease.
glioblastoma (continued). "This dynamic positions MGMT methylation as both a prognostic and predictive biomarker essential for patient stratification in glioblastoma therapies." (PMID 40895460, 2025). "A study delved into the value of the application of DCE imaging technology in the assessment of MGMT promoter methylation status in glioblastoma." (PMID 39944537, 2025). "A significantly larger survival benefit was reported from adding temozolomide to standard radiotherapy in MGMT-methylated glioblastomas compared to the MGMT-unmethylated group." (PMID 40183077, 2025). "In summary, our study provides compelling evidence that SQ-TMZ NPs offer a significant therapeutic advantage over free TMZ by improving drug stability, enhancing BBB penetration, and overcoming MGMT-mediated resistance in glioblastoma cells." (PMID 40429865, 2025). "Glioblastoma cell lines expressing elevated levels of MGMT, such as LN18 and T98G, exhibit resistance to TMZ." (PMID 40141405, 2025). "Current investigations include an ongoing phase III randomized trial evaluating DCVax-L combined with radiotherapy specifically in MGMT-methylated glioblastoma patients to further validate these promising findings (NCT03548571)." (PMID 40386781, 2025). "Three primary human glioblastoma MGMT promoter hypermethylated cell populations (G35, G71, and G106) deduced from intraoperative surgical specimens were used for the following experiments." (PMID 39680504, 2025). "O‐6‐methylguanine DNA methyltransferase (MGMT) promoter methylation status is a critical prognostic factor in glioblastoma." (PMID 41277375, 2025). "Temozolomide (TMZ), the frontline chemotherapeutic agent for glioblastoma, frequently encounters resistance due to the upregulation of O6-methylguanine-DNA methyltransferase (MGMT), an enzyme that counteracts the alkylating effects of TMZ." (PMID 40564985, 2025). "In summary, this study, along with previous research, enhances our understanding of the role and associations of methylation in intergenic and intragenic enhancers of MGMT in glioblastoma." (PMID 40244270, 2025). "Temozolomide added to radiotherapy improves overall survival in glioblastoma, especially in tumors with MGMT promoter methylation." (PMID 41301694, 2025). "Within the realm of DNA damage repair, CRISPR-Cas9 downregulation of MGMT expression has been found to reverse TMZ resistance in glioblastoma cell lines." (PMID 40868217, 2025). "The panelists agreed that, in patients with confirmed glioblastoma (IDH-wildtype) or grade 4 IDH-mutated astrocytoma, MGMT promoter methylation status should be tested to inform prognosis and predict response to temozolomide chemotherapy." (PMID 40277764, 2025). "The landmark Stupp trial, for instance, demonstrated that adding temozolomide to postoperative radiotherapy improved median survival in glioblastoma by roughly 2.5 months, an effect most pronounced in MGMT-methylated patients." (PMID 41398783, 2025). "Patients treated with temozolomide for glioblastoma multiforme showing low MGMT expression and MGMT promoter methylation exhibit improved response and survival." (PMID 41375037, 2025). "Representative examples include case 3 (KRAS-mutant metastatic CRC post 6 lines of therapy) and case 15 (glioblastoma with hypermethylated MGMT promoter and multiple amplifications)." (PMID 40973166, 2025). "Previous studies show that glioblastomas with MGMT promoter methylation exhibit higher minimum ADC values than unmethylated cases, which is consistent with the present findings." (PMID 40958862, 2025). "While the precise mechanisms remain to be fully elucidated, these findings provide a strong rationale for co-targeting RBM39 and MGMT to overcome temozolomide resistance in cancers with high MGMT expression, including glioblastoma and neuroendocrine neoplasms." (PMID 41300971, 2025). "For glioblastomas, MGMT-methylated tumors are also more sensitive to chemotherapy than unmethylated MGMT tumors." (PMID 40137412, 2025).
glioblastoma (continued). "Resistance to alkylating chemotherapeutic agents such as temozolomide (TMZ) is a significant challenge in treating tumors with high MGMT expression, including MGMT-positive glioblastoma and neuroendocrine neoplasms." (PMID 41300971, 2025). "For glioblastoma patients with MGMT promoter methylation, TMZ is especially beneficial and is associated with longer progression-free and overall survival." (PMID 39796773, 2025). "These insights provide a foundation for future research aimed at refining treatment strategies for MGMT-methylated glioblastoma patients, offering a more individualized approach to optimize clinical outcomes." (PMID 39851494, 2025). "MGMT promoter methylation in glioblastoma enhances responsiveness to alkylating agents such as BCNU (carmustine) and temozolomide, contributing to progression-free survival." (PMID 40546613, 2025). "Beyond MGMT and TERT alterations, chromosomal aberrations are hallmark features of IDH-wildtype glioblastoma, particularly chromosome 7 gain (+7) and chromosome 10 loss (−10), which contribute to genomic instability and tumor aggressiveness." (PMID 41346390, 2025). "The safety and efficacy of TamferonTM, is evaluated in patients with MGMT-unmethylated glioblastoma (NCT03866109)." (PMID 41208963, 2025). "By stratifying patients according to MGMT methylation status, clinicians can optimize therapeutic regimens, minimize treatment-related toxicity, and improve outcomes for glioblastoma patients, particularly in cases where resistance is suspected." (PMID 40806492, 2025). "Unlike some previous investigations, this analysis provides a clinicopathologically uniform cohort of newly diagnosed MGMT promoter methylated glioblastoma patients with exclusively IDH wild‐type tumors and a balanced control cohort." (PMID 40260649, 2025). "Further studies with larger patient cohorts are needed to validate the clinical relevance of intergenic and intragenic MGMT enhancer methylation in glioblastoma." (PMID 40244270, 2025). "It was demonstrated that delivering MGMT via lentiviral vectors into glioblastoma cells restored repair capacity, increasing resistance to alkylating agents like TMZ." (PMID 40895460, 2025). "The combination of CCNU and temozolomide is currently a frequently used treatment for MGMT promoter methylated glioblastoma patients." (PMID 40260649, 2025). "Temozolomide is currently only approved by the FDA for patients with glioblastoma multiforme (GBM) or anaplastic astrocytoma, but response to temozolomide is associated with MGMT deficiency and a functional DNA MMR pathway in several different cancer types." (PMID 40458731, 2025). "The O6-methylguanine-DNA methyltransferase (MGMT) promoter methylation status is also frequently assessed, since the MGMT status in glioblastoma is both predictive of the response to chemotherapy and an independent prognostic variable." (PMID 40560014, 2025). "A number of systematic reviews and meta-analyses have validated the predictive function of MGMT promoter methylation in glioblastoma." (PMID 41311621, 2025). "The efficacy of temozolomide varies across different glioblastomas with known predictors of response (e.g., MGMT methylation status)." (PMID 40378113, 2025). "Overall, MGMT’s role in resistance to chemotherapy and radiotherapy underscores the necessity for tailored therapeutic strategies in oncology, particularly for glioblastoma patients." (PMID 40895460, 2025). "High recurrence after treatment and activity is restricted to MGMT promoter‐methylated glioblastoma." (PMID 40014265, 2025). "The recent age-stratified analysis of the RANO resection group showed that survival benefit from supramaximal resection with low residual NCE tumor volume was mainly observed in MGMT-unmethylated glioblastoma." (PMID 41247617, 2025). "We developed a method to find the optimal gray zone using pyrosequencing MGMT methylation values (CpG sites 72–83) from 308 glioblastoma cases with overall survival data." (PMID 40444102, 2025).
glioblastoma (continued). "MGMT promoter methylation in glioblastoma is both a prognostic marker and a predictive one for response to treatment with alkylating agents." (PMID 40183077, 2025). "Glioblastoma has been a key focus for imaging–omics integration, particularly in predicting the methylation status of MGMT from MRI along with epigenomic data, offering non-invasive biomarkers for clinical decision making." (PMID 41301005, 2025). "Another highly clinically relevant example of epigenetic heterogeneity is the hypermethylation of the MGMT gene in glioblastoma." (PMID 39941808, 2025). "The contribution of epigenetic deregulation to inter-patient heterogeneity has been demonstrated, including differential methylation at the promoter of the MGMT gene which is to date the only biomarker predicting drug response in glioblastoma patients." (PMID 39915814, 2025). "For example, methylation of the O6-methylguanine-DNA methyltransferase (MGMT) promoter in glioblastoma silences DNA repair capability, rendering tumors more susceptible to alkylating agents such as temozolomide." (PMID 41301080, 2025). "In our multicentric analysis, featuring data from five neuro‐oncology centers in Germany, we investigated the prognostic value of TMT using a homogeneous cohort of newly diagnosed MGMT promoter methylated glioblastoma patients." (PMID 40260649, 2025). "Concomitant chemoradiotherapy yields a greater survival benefit in patients with MGMT (O6-methylguanine DNA methyltransferase) promoter methylation, a biomarker with both prognostic and therapeutic implications for glioblastoma management." (PMID 41301694, 2025). "The status of MGMT promoter methylation is well-established as a positive prognostic factor in glioblastomas." (PMID 40002479, 2025). "Treatment of glioblastoma cell lines with temozolomide in vitro led to a significant increase in expression of MGMT, leading to resistance to temozolomide treatment." (PMID 39796751, 2025). "In glioblastoma, MGMT promoter hypermethylation is a well-established predictive biomarker for TMZ sensitivity and improved overall survival, making it a standard-of-care marker in neuro-oncology." (PMID 40895460, 2025). "Although related studies have assessed the molecular mechanism regulating MGMT in glioblastoma, the signal transduction pathway regulating MGMT in melanoma cells has not been elucidated." (PMID 39873425, 2025). "The response of glioblastoma patients to TMZ is critically influenced by the DNA methylation status of the MGMT promoter." (PMID 40244270, 2025). "Abnormal MGMT regulation is often observed in cancers like glioblastoma, colorectal, lung, and cervical cancer, where it affects sensitivity to alkylating chemotherapies." (PMID 40895460, 2025). "While adult glioblastoma resistance typically develops from EGFR amplification or MGMT promoter methylation, pediatric H3K27M-mutant tumors evade treatment by employing chromatin remodeling and disrupted developmental processes (e.g., PRC2 dysfunction)." (PMID 40564017, 2025). "In glioblastoma, promoter hypermethylation of the DNA repair gene MGMT reduces DNA repair capacity, confers sensitivity to alkylating chemotherapy such as temozolomide, and remains one of the most robust predictive biomarkers in neuro-oncology." (PMID 41341594, 2025). "Significant differences in enhancer methylation between these two age groups were found exclusively for intergenic enhancers and only in MGMT promoter unmethylated glioblastoma samples." (PMID 40244270, 2025). "Our results suggest a significant association of enhancer methylation with MGMT promoter methylation, MGMT expression, and clinical and demographic characteristics in glioblastoma." (PMID 40244270, 2025). "In their analysis, patients with IDH-wt glioblastoma had a median survival of 17.1 months when the MGMT promoter was methylated and 12.4 months when it was unmethylated." (PMID 41541926, 2025).
glioblastoma (continued). "Sumaiya Fazal (March 2025) introduced ADAPT (Adaptive Sparse Autoencoders), an innovative method for determining MGMT methylation status in glioblastoma patients using MRI images." (PMID 41295120, 2025). "This year also introduced a new task of evaluating classification methods to predict MGMT promoter methylation status, aiding in precise glioblastoma diagnosis and treatment planning." (PMID 40292960, 2025). "Quantitative analysis of IF staining revealed a positive correlation between USP7 and MGMT expression levels (p < 0.01, n = 62 glioblastoma samples)." (PMID 40835840, 2025). "AI-guided molecular profiling and treatment response prediction models can facilitate individualized chemotherapy regimen tailoring, especially for glioblastomas with MGMT promoter methylation." (PMID 41007844, 2025). "DNA methylation status in glioblastomas, with MGMT values above 10% (10–50% and >50%), correlated with an age of patients over 50 years (p = 0.016), incomplete treatment (p = 0.030), and a lower resectability rate (p = 0.034)." (PMID 40002588, 2025). "ADAPT offers a promising advancement for personalized treatment plans in glioblastoma by improving the accuracy of MGMT methylation status prediction." (PMID 41295120, 2025). "The delivery of pCas9/MGMT downregulated MGMT expression, enhanced the sensitivity of glioblastoma cells to temozolomide, and improved the therapeutic efficacy of the drug in glioblastoma treatment." (PMID 39942646, 2025). "Radiomic features extracted from DTI and other imaging sequences have been shown to correlate with glioblastoma molecular subtypes, including IDH mutation, MGMT methylation, and EGFR amplification." (PMID 40563748, 2025). "In 60% of patients with truly MGMT unmethylated glioblastomas, the benefit from the addition of temozolomide to radiation is very limited." (PMID 40225909, 2025). "Another important biomarker for both astrocytoma and glioblastoma patients is O6-methylguanine DNA methyltransferase (MGMT) promoter methylation." (PMID 39859375, 2025). "The prediction of MGMT status in glioblastoma using radiogenomics began with studies focusing on radiomics signatures." (PMID 41277375, 2025). "MGMT-methylated glioblastomas show higher ADC values on diffusion MRI, indicating lower cellularity." (PMID 41247617, 2025). "In this line, FANCI knockout did not induce TMZ hypersensitivity, consistent with what was observed in an MGMT-positive subset of glioblastomas." (PMID 39656916, 2025). "The methylation of MGMT was originally recognized as prognostic and predictive in glioblastoma (GBM) patients getting treatment with temozolomide." (PMID 40792048, 2025). "Several CpGs in intragenic enhancers exhibited higher methylation levels than most glioblastoma samples with methylated MGMT promoter." (PMID 40244270, 2025). "Glioblastomas can often hijack these mechanisms to alter DNA repair capacity(e.g., MGMT) or prevent senescence (e.g., TERT)." (PMID 40378113, 2025). "O6-methylguanine-DNA methyltransferase (MGMT) is a critical clinical biomarker for those diagnosed with glioblastoma." (PMID 39796751, 2025). "The methylation status of the MGMT gene promoter is recognized as a key predictive biomarker for glioblastoma patients, influencing treatment decisions and outcomes." (PMID 40244270, 2025). "One specific example is in glioblastomas, i.e., the methylation of the MGMT promoter silences a DNA repair enzyme which increases the sensitivity of the cells to the alkylating chemotherapeutic." (PMID 40806492, 2025). "Second, due to limited data availability, this study did not include other potential prognostic factors associated with glioblastoma, such as KPS scores, MGMT status, and extent of resection." (PMID 40459512, 2025).
glioblastoma (continued). "Developing an MGMT status classification system for glioblastoma based on MRI would eliminate the need for additional examinations, offering significant advantages for both diagnosis and treatment planning, this study will focus on this problem." (PMID 41277375, 2025). "Traditional prognostic factors in glioblastoma include age, performance status, extent of resection, and molecular markers such as isocitrate dehydrogenase (IDH) mutation and O6-methylguanine-DNA methyltransferase (MGMT) promoter methylation." (PMID 41523502, 2025). "MGMT status remains one of the strongest established prognostic and predictive biomarkers in glioblastoma, particularly for response to temozolomide." (PMID 41114777, 2025). "The proposed framework demonstrated superior performance in predicting MGMT promoter methylation status in glioblastoma patients compared to conventional methods, achieving a classification accuracy of 95% and an AUC of 0.96." (PMID 41295120, 2025). "Approximately 50–60% of patients with glioblastoma have tumours with an unmethylated MGMT promoter, and their estimated 2-year survival rate is less than 10%." (PMID 41194660, 2025). "Intratumoral epigenetic plasticity manifests as dynamically shifting methylation landscapes that evade single-timepoint assays clinically evidenced by MGMT promoter reversion in 37% of recurrent glioblastoma patients." (PMID 41301752, 2025). "In this multicenter real‐world analysis, we demonstrated that temporal muscle thickness at baseline and over time serves as a robust prognostic biomarker in newly diagnosed MGMT promoter methylated glioblastoma patients treated with radiochemotherapy." (PMID 40260649, 2025). "In conclusion, this retrospective study suggests a potential prognostic value of EGFR amplification and MGMT promoter methylation in IDH-wild-type glioblastoma treated with standard chemoradiotherapy." (PMID 40722305, 2025). "MRI studies have shown that MGMT-methylated glioblastomas exhibit reduced perfusion and blood flow compared to unmethylated tumors." (PMID 41247617, 2025). "MGMT is a critical prognostic factor in glioblastoma, and this study proposed a novel method for diagnosing MGMT status in a quick and non‐invasive manner based on mpMRI." (PMID 41277375, 2025). "In IDH-wt glioblastoma response to alkylating chemotherapy is better in tumors with methylated MGMT promoter [29 P]romoter methylation is detected in about 40% of all patients with IDH-wt astrocytomas and IDH-wt glioblastomas." (PMID 41466163, 2025). "MGMT (O6-methylguanine-DNA methyltransferase) promoter methylation is one of the foremost well-established prescient biomarkers in glioblastoma." (PMID 41311621, 2025). "The patient #3 was a 64-year-old male, who was diagnosed with right temporal IDH wildtype glioblastoma with an unmethylated MGMT promoter in March 2021." (PMID 40295665, 2025). "Multivariate analysis appreciates a positive correlation between overall survival in glioblastoma patients and clinicopathological factors such as age, MGMT, survivin expression, and survivin localization." (PMID 40422257, 2025). "First, our cohort had insufficient information on MGMT methylation status, a significant prognostic factor for glioblastoma." (PMID 41473753, 2025). "Search terms, including “MGMT”, “methylation”, “glioma”, “glioblastoma”, “machine learning”, “deep learning”, and “radiomics”, were adopted in various MeSH combinations." (PMID 39941181, 2025). "MGMT promoter methylation reduces the intracellular level of MGMT and is correlated with improved progression-free and overall survival in glioblastoma patients treated with alkylating agents." (PMID 41300971, 2025).